KRT86 (keratin 86)
Description:
Structural component of intermediate filaments in the hair shaft. Forms obligate heterodimers with type I hair keratins, which assemble into keratin intermediate filaments that contribute to the structural integrity and mechanical strength of the hair shaft.
Synonyms: K86; KRTHB6; MNX; Hb6; Hb1; KRTHB1; NMLIX1
Tractability: PROTAC: UniProt records ubiquitination sites on it; ubiquitination databases record sites on it.
Target class: Structural protein
Gene: Protein-coding gene on chromosome 12 (52,249,300 to 52,309,163, forward strand). Ensembl gene ENSG00000170442.
Subcellular location (Human Protein Atlas): Cytosol
Pathways (Reactome):
Developmental Biology: Formation of the cornified envelope; Keratinization
Gene Ontology:
Molecular function: protein binding; structural constituent of skin epidermis
Biological process: intermediate filament organization; keratinization
Cellular component: extracellular region; keratin filament; cytosol
Genetic constraint (gnomAD): Loss-of-function variants: 27 observed, 35.65 expected, observed/expected ratio (o/e) 0.76, 90% interval 0.56 to 1.04. The upper end of that interval is the gene's LOEUF score, 1.04, which puts it in group 4 of 6, group 1 being the genes least tolerant of losing a copy. Missense variants: 511 observed, 483.71 expected, observed/expected ratio (o/e) 1.06, 90% interval 0.98 to 1.14. Synonymous variants: 213 observed, 196.64 expected, observed/expected ratio (o/e) 1.08, 90% interval 0.97 to 1.21.
Homologues: Orthologues: macaque KRT86 (98% identical), chimpanzee KRT86 (91% identical), dog KRT81 (87% identical). Paralogues in human: KRT81 (94% identical), KRT83 (91% identical), KRT85 (84% identical), KRT84 (62% identical), KRT82 (58% identical), KRT5 (52% identical), KRT6A (51% identical), KRT6C (51% identical), KRT6B (51% identical), KRT3 (49% identical), KRT75 (49% identical), KRT8 (48% identical), and 56 more.
Diseases named in the same sentence as KRT86 in open-access papers:
KRT86 is named in the same sentence as 9 diseases in open-access papers, as found by Europe PMC text mining. Sharing a sentence is not in itself a finding about the gene and the disease. The quoted sentences say what the papers report.
monilethrix (2 papers, 2011 to 2022). Monilethrix is a rare genodermatosis characterized by a hair shaft dysplasia resulting in hypotrichosis. "Specifically, mutations in the 1A and 2B domains of KRT81, KRT83, and KRT86 resulted in Monilethrix, a rare monogenic hair loss disorder 28,35." (PMID 35145093, 2022). "The R430Q mutation of the KRT86 gene may be pathogenic for monilethrix." (PMID 23554671, 2011). "In this study, we have identified a Chinese family with monilethrix, and sequenced three keratin genes (KRT81, KRT83, and KRT86) of the subjects to elucidate the underlying molecular basis of this disorder." (PMID 23554671, 2011).
alopecia areata (1 paper, 2020). Loss of scalp and body hair involving microscopically inflammatory patchy areas. "In alopecia areata (AA) lesional skin, Krt85 and Krt86 were significantly repressed." (PMID 32028879, 2020).
lung carcinoma (1 paper, 2024). "These T cells appeared to resemble a recently described IL7R-HAVCR2+KRT86+DUSP4+LAYN+ subset, which has been associated with response to anti-PD1 therapy in lung cancer." (PMID 39312285, 2024).
tumor (3 papers, 2022 to 2025). "Subclustering of natural killer (NK) cells revealed well-known NCAM1- and FCGR3A- expressing subsets and an interesting keratin (KRT81 and KRT86)-expressing subset potentially enriched in tumor tissues." (PMID 36423636, 2022). "The four most significantly downregulated genes in COM, compared to healthy tissue controls, were all keratin genes (KRT33A, KRT86, KRT34, and KRT38), which is consistent with a potential loss of epithelial differentiation, a hallmark of aggressive tumor behavior." (PMID 40647405, 2025).
KRT86 also shares sentences with these, for which no sentence is quoted: epidermolysis bullosa simplex (1 paper); epidermolytic ichthyosis (1); hypotrichosis (1); pachyonychia congenita (1); skin disorder (1).